SMARCB1 (SWI/SNF related BAF chromatin remodeling complex subunit B1)
Diseases named in the same sentence as SMARCB1 in open-access papers (continued):
Sharing a sentence is not in itself a finding about the gene and the disease.
epithelioid sarcoma (continued). "The diagnosis is all the more challenging that other poorly differentiated cancers lose SMARCB1 expression, such as epithelioid sarcomas (ES), renal medullary carcinomas (RMC) or undifferentiated chordomas (UC)." (PMID 28427232, 2017). "Methylation studies on SMARCB1‐deficient tumours, although not including epithelioid sarcomas, reported methylation subgroups which resulted in new clinical stratification and therapeutic approaches." (PMID 37316954, 2023). "The differentiation between epithelioid sarcoma, MRT and SMARCB1 deficient carcinoma might only be possible with the help of molecular profiling." (PMID 35864317, 2022). "Similarly, the morphologic features of these lesions are wholly dissimilar from those of epithelioid sarcoma, and they show retained SMARCB1 expression." (PMID 33742141, 2021). "Epithelioid sarcoma may mimic ALCL, but this tumor is positive for vascular markers (CD34, ERG, FLI1), cytokeratin, and shows loss of INI1/SMARCB1." (PMID 34572893, 2021). "More importantly, the loss of SMARCB1/INI1 leads to the deregulation of EZH2, and drugs targeting EZH2 have been proven successful in controlling tumor growth and are currently approved to be used in treating epithelioid sarcoma." (PMID 33072594, 2020). "In addition, miR-671-5p has been showed to silence the SMARCB1 expression in epithelioid sarcoma and to repress BCL2L12 expression in melanoma." (PMID 26588055, 2016). "The negativity of epithelioid sarcoma for p63, which is usually positive in adnexal neoplasms, as well as the loss of the protein SMARCB1/INI1 excludes the possibility of an adnexal neoplasm." (PMID 23691400, 2013). "SMARCB1 has been shown to be frequently inactivated in epithelioid sarcomas." (PMID 21625565, 2011). "SMARCB1 loss of function is also reported in other sarcomas that affect children and young people, including synovial sarcoma, the epithelioid variant of the malignant peripheral nerve sheath tumour (MPNST), epithelioid sarcoma, and the paediatric subtype of chordoma, poorly differentiated chordoma." (PMID 40983796, 2025). "Epithelioid sarcoma (ES) is a rare subtype of soft-tissue sarcoma of uncertain cellular origin that is characterized by failed expression of the SMARCB1/INI1 tumor-suppressor gene." (PMID 38310286, 2024). "High proliferation (> 40%) was observed in melanoma, epithelioid sarcoma (ES), malignant SFT, and SMARCB1- and SMARCA4-deficient neoplasms." (PMID 34350470, 2021). "Concerning the absence of SMARCB1 in different types of tumors, such as epithelioid sarcomas and renal medullary carcinomas, the loss of SMARCB1 expression may be a biological event of uncertain prognostic significance." (PMID 27733182, 2016). "In the majority of cases we see a relation to known SMARCB1 driven sarcomas such as MRT (patient 4) and epithelioid sarcoma (patients 1, 2, 3, 5, and 7)." (PMID 35864317, 2022). "Based on our analyses performed, we show that SMARCB1 (INI1)-deficient neoplasms are very rare and most likely represent a spectrum of known tumor types, namely epithelioid sarcoma, MRT and undifferentiated carcinoma rather than a distinct entity." (PMID 35864317, 2022). "The prototypical SMARCB1-deficient cancer is MRT, but numerous other tumor types with the complete loss of SMARCB1 have been described such as renal medullary carcinoma (RMC), epithelioid sarcoma (ES), and pediatric poorly differentiated chordoma, almost all of which have a poor prognosis." (PMID 35892904, 2022). "Unlike MRT, epithelioid sarcomas harbor in addition to SMARCB1 (INI1) alterations multiple copy number gains and losses throughout the genome as seen for example in case 1 and 7, in contrast to case 419,29." (PMID 35864317, 2022). "Cutaneous syncytial myoepithelioma is positive for S100 protein and negative for ALK, whereas epithelioid sarcoma shows greater nuclear atypia than EFH and loss of SMARCB1 (INI1) expression." (PMID 32316685, 2020).
epithelioid sarcoma (continued). "SMARCB1 expression is absent in 83% of epithelioid sarcomas, and inactivation of SMARCB1 results in aggressive tumorigenesis." (PMID 33324542, 2020). "In addition, the efficacy of EZH2 inhibitors in patients with advanced SMARCB1-negative epithelioid sarcoma has been reported." (PMID 36732357, 2023). "While the impact of these aberrations remains unclear, it may well be supposed that SMARCB1 might not be the only oncogenic driver of RMCs, just as it is already presumed for epithelioid sarcomas." (PMID 36291828, 2022). "Epithelioid sarcomas lack intracytoplasmic vacuoles and do not express SMARCB1 (INI1)." (PMID 32316685, 2020). "The loss of SMARCA4 (BRG-1) can exceptionally occur in tumors such as SMARCB1/INI1-retained epithelioid sarcoma (ES); in this context, the absence of SOX2 and SALL4 expression aids in distinguishing ES from SMARCA4-UT." (PMID 38265099, 2024). "Proximal-type epithelioid sarcoma has similarities with MRT, including the lack of nuclear immunoreactivity of SMARCB1 (also known as INI1, BAF47, and hSNF5)." (PMID 25165708, 2014).
schwannomatosis (72 papers, 2009 to 2025). The least frequent form of the rare genetic disorder neurofibromatosis. "Schwannomatosis is caused by mutations in the SMARCB1 or LZTR1 genes, which are involved in regulating cell growth and tumor suppression." (PMID 40764996, 2025). "This mosaic staining pattern is less common in sporadic schwannomatosis-associated schwannomas and uncommon in isolated schwannomas, which normally show diffuse SMARCB1 staining." (PMID 41284083, 2025). "Until the identification of the schwannomatosis-causing genes LZTR1 and SMARCB1, schwannomatosis was mainly identified by clinical criteria and by the exclusion of germline NF2 PVs." (PMID 40794298, 2025). "Approximately 40% of cases show mosaic loss of nuclear SMARCB1/INI1 expression, a pattern often associated with schwannomatosis and familial tumor syndromes." (PMID 40666544, 2025). "This mouse model of schwannoma development impressively reproduces the genetic profile of schwannomatosis-associated schwannomas with concomitant loss of both Smarcb1 and Nf2." (PMID 40794298, 2025). "Four families have so far been reported, with carriers of germline pathogenic SMARCB1 variants having either schwannomatosis or MRT." (PMID 40794298, 2025). "Germline mutations in SMARCB1 are responsible for 48% of familial and 10% of sporadic schwannomatosis cases, while mutations in LZTR1 account for 38% of familial and 30% of sporadic schwannomatosis cases." (PMID 40337438, 2025). "Since the wild-type SMARCB1 allele is often lost in schwannomas of patients with schwannomatosis, the SMARCB1 protein detected in schwannoma cells must be encoded by the mutant allele." (PMID 40794298, 2025). "Now the molecular mechanism of schwannomatosis is thought to consist of mutations in two genes SMARCB1 and LZTR1." (PMID 40337438, 2025). "Molecular testing in their father with a history of schwannomatosis revealed a germline SMARCB1 variant." (PMID 41514521, 2025). "Patients with schwannomatosis develop multiple peripheral schwannomas and, less frequently, meningiomas from inactivating mutations of SMARCB1 or LZTR1." (PMID 39170644, 2024). "Our patient supports the theory that the initial hit for schwannomatosis results from a germline SMARCB1 mutation." (PMID 39170644, 2024). "Contrastingly, SMARCB1 pathogenic variations in schwannomatosis patients are categorized as familial or sporadic, comprising approximately 48% and 10% of schwannomatosis cases, respectively." (PMID 39170644, 2024). "Although SMARCB1 is mutated in schwannomatosis and CSS, the literature describes one confirmed case of a CSS patient presenting with schwannomatosis and a SMARCB1 pathogenic variant." (PMID 39170644, 2024). "Schwannomatosis is an autosomal dominant disorder characterized by the development of multiple schwannomas, and it is caused by mutations in the SMARCB1 and LZTR1 genes." (PMID 37240461, 2023). "Germline pathogenic variant in SMARCB1 or LZTR1 strongly suggest the diagnosis of schwannomatosis for patients with a proven schwannoma." (PMID 36440500, 2023). "Germline mutations in PTEN and SMARCB1, causing Cowden syndrome and schwannomatosis, respectively, are also suggested to increase risk of ULs, although the association is much less clear." (PMID 36773604, 2023). "In contrast, schwannomatosis originates from mutations in either the integrase interactor 1 (INI1/SMARCB1) gene or the LZTR1 gene." (PMID 37181996, 2023). "Germline missense mutations and in-frame deletions within the WHD of SMARCB1 have been linked to schwannomatosis, a condition predisposing patients to forming benign tumors that develop in the CNS called schwannomas." (PMID 35892904, 2022). "Schwannomatosis was first linked to the tumour suppressor gene SMARCB1/INI1 located on chromosome 22, which at present accounts for approximately 40–50% of familial schwannomatosis and 10% of sporadic cases." (PMID 35698239, 2022).
schwannomatosis (continued). "In 2007 a separate gene on chromosome 22 called SMARCB1 was found to cause a subset of familial and sporadic/isolated cases of schwannomatosis." (PMID 35361920, 2022). "Most patients with schwannomatosis express germline SMARCB1 missense variants, in‐frame deletions, or splice‐site variants, mainly located at the 5′‐end or 3′‐end of the gene." (PMID 35391499, 2022). "Malignant-Peripheral-Nerve-Sheath-Tumour-MPNST should be suspected in anyone with rapidly growing tumours and/or functional loss especially with SMARCB1-related schwannomatosis." (PMID 35361920, 2022). "Due to the increased malignancy risk in schwannomatosis associated with SMARCB1 this additional step is important as when found it allows confirmation of the diagnosis and the ability to offer pre-symptomatic testing to relatives." (PMID 35361920, 2022). "The gene, which is centromeric to NF2 and SMARCB1 on chromosome 22q11.21, was recently uncovered as a germline predisposition gene in schwannomatosis." (PMID 36008825, 2022). "The genetic characteristics of disease‐associated SMARCB1 variants have already been studied and genotype–phenotype correlations have been identified between schwannomatosis and other disorders." (PMID 35391499, 2022). "Genotype phenotype correlations are nonetheless strong with only minor overlap between rhabdoid predisposition and schwannomatosis with SMARCB1." (PMID 35361920, 2022). "SMARCB1 loss in the early neural crest results in the development of human rhabdoid tumors, while induced loss at a later stage results in Schwannomatosis." (PMID 33262459, 2021). "In schwannomatosis, exon 1 mutations and re-initiation of translation associated with mosaic SMARCB1 staining pattern have been described." (PMID 34003336, 2021). "Until recently, the presence of vestibular schwannoma excluded a diagnosis of schwannomatosis but patients with SMARCB1 and LZTR1 pathogenic variants that met neurofibromatosis type 2 (NF2) criteria have been described." (PMID 32575496, 2020). "Germline mutation of the SMARCB1 gene on 22q11.23 causes several hereditary conditions, such as rhabdoid tumor predisposition syndrome (AT/RT), schwannomatosis, and Coffin-Siris syndrome." (PMID 33194703, 2020). "Several hereditary conditions are associated with germline mutation of the SMARCB1 gene on 22q11.23, including schwannomatosis, rhabdoid tumor predisposition syndrome [atypical teratoid/rhabdoid tumor (AT/RT)], and Coffin-Siris syndrome." (PMID 33194703, 2020). "To date, a single CSS individual with a germline missense SMARCB1 mutation has been reported to suffer from a SMARCB1-related tumor entity, namely schwannomatosis, a benign tumor disease." (PMID 31273213, 2019). "So far, only four families have been reported, with germline SMARCB1 mutation carriers being either affected by schwannomatosis or RT." (PMID 29779243, 2018). "Our findings suggest that long‐term survivors of AT/RT and truncating germline SMARCB1 mutations should receive regular surveillance for schwannomatosis‐associated clinical symptoms." (PMID 29779243, 2018). "Our findings indicate that schwannomatosis‐associated tumorigenesis and related clinical symptoms need to be taken into account in patients surviving RTs and harboring germline SMARCB1 mutations." (PMID 29779243, 2018). "The overlap with NCBRS is supported by the description of a patient with a SMARCB1 mutation who also developed schwannomatosis due to additional somatic loss of both NF2 copies." (PMID 30123105, 2018). "In contrast to LZTR1-associated schwannomatosis, SMARCB1 mutations are probably less likely to predispose to unilateral vestibular schwannomas." (PMID 27921248, 2017).
schwannomatosis (continued). "Three families have been reported with germline SMARCB1 mutation carriers presenting either with rhabdoid tumours or schwannomatosis." (PMID 27921248, 2017). "So far, only one solitary case of a unilateral vestibular schwannoma in a putative SMARCB1-associated schwannomatosis family has been reported." (PMID 27921248, 2017). "Further studies are necessary to assess the MPNST risk for patients with SMARCB1 mutation-positive schwannomatosis." (PMID 27921248, 2017). "Since, in schwannomas of patients with schwannomatosis, the wild-type SMARCB1 allele is often lost by deletion or monosomy 22, the SMARCB1 protein detected in schwannoma cells must be encoded by the mutant allele." (PMID 27921248, 2017). "These authors analysed four schwannomatosis-associated SMARCB1 mutations that were located in the 5′ region of the gene and were predicted to introduce a premature translational termination codon (PTC)." (PMID 27921248, 2017). "In contrast to this situation, SMARCB1 mutations causing schwannomatosis are predominantly located at the 5′ or 3′ end of the gene." (PMID 27921248, 2017). "SMARCB1 germline mutations have been found in 45% of familial probands and 7% of sporadic schwannomatosis patients." (PMID 28824165, 2017). "Differences in the position and type of germline SMARCB1 mutations have been observed in patients with schwannomatosis compared to those with rhabdoid tumours." (PMID 27921248, 2017). "Schwannomatosis-associated SMARCB1 mutations are preferentially located either at the 5′or 3′ end of the gene." (PMID 27921248, 2017). "Taken together, these observations suggest that in schwannomatosis, germline SMARCB1 mutations encode proteins with some residual functionality." (PMID 27921248, 2017). "This is in stark contrast to the schwannomatosis-associated tumours which usually exhibit mosaic SMARCB1 expression." (PMID 27921248, 2017). "A patient with Coffin-Siris syndrome phenotype and a constitutional missense SMARCB1 gene mutation developed schwannomatosis." (PMID 26803492, 2016). "Schwannomatosis is partially explained by mutations in the SMARCB1 gene, located 6 Mb centromeric to the NF2 gene at 22q11.23." (PMID 25739810, 2015). "The results highlight the importance of undertaking a mutational analysis for NF2 and SMARCB1 in at least 2 schwannomas in sporadic patients with a Schwannomatosis phenotype before concluding a clinical diagnostics." (PMID 25739810, 2015). "All five patients carrying a SMARCB1 mutation had more multiple schwannomas, corresponding to 10.2% of patients with schwannomatosis." (PMID 21255467, 2011). "Germline SMARCB1 mutations have been recently described in rare families with predisposition to RT and to schwannomatosis." (PMID 19221586, 2009). "This review focuses on the germline pathogenic SMARCB1 variants responsible for a number of completely different diseases including schwannomatosis, RTPS1 and syndromic neurodevelopmental disorders as well as the functional impact of SMARCB1 loss in the context of these very different pathologies." (PMID 40794298, 2025). "However, the loss of the wild-type SMARCB1 allele is insufficient for schwannoma growth which appears to be dependent upon concomitant somatic NF2 PVs in patients with SMARCB1-related schwannomatosis according to the four-hit/three-step model of tumorigenesis." (PMID 40794298, 2025). "Pathogenic variants (PVs) in LZTR1 or SMARCB1 are detected in approximately 86% of familial and ∼40% of sporadic schwannomatosis cases utilizing standard clinical mutation analysis including exons and intronic segments at exon boundaries (typically ± 20 nucleotides)." (PMID 40794298, 2025).